NECTIN2 (nectin cell adhesion molecule 2)
Diseases named in the same sentence as NECTIN2 in open-access papers (continued):
Sharing a sentence is not in itself a finding about the gene and the disease.
tumor (continued). "A similar modulation was observed also for Nectin-2 (CD112) that, when overexpressed, facilitates tumor cell proliferation, increases invasiveness and migration." (PMID 37435061, 2023). "In further studies, Nectin2 expression in the tumor tissue of NB patients will be determined to explore the reason for the increase in Nectin2." (PMID 36916296, 2023). "CD226 (also known as DNAM-1) and CD112 (nectin-2) are also cell surface receptors that are expressed on various immune cells, including T cells, NK cells, and DCs, as well as on many tumor cells." (PMID 37345057, 2023). "Panobinostat also upregulated expression of the activating ligands CD80, CD86, and Nectin-2 in tumor cells, promoting NK cell cytolytic effect." (PMID 37090711, 2023). "Molfettaet al. demonstrated that Nectin2 is ubiquitinated on tumor cells and that this modification can promote protein degradation." (PMID 36916296, 2023). "The expression of nectin-2 was significantly higher in the tumor specimens compared to the corresponding liver tissue." (PMID 37568798, 2023). "The current study identified the upregulation of Nectin2 expression in NB patients and its correlation with advanced tumor staging." (PMID 36916296, 2023). "Existing intriguing reports on the significance of nectin-2 in neoplastic disease encourage further research in this area." (PMID 37958883, 2023). "DNAM-1 is an activating receptor that binds PVR and Nectin2 adhesion molecules frequently overexpressed on the surface of cancerous cells, thus representing a central receptor in tumor recognition." (PMID 37760586, 2023). "Overall, these trials suggest that blocking the PVRIG/NECTIN-2 interaction to enhance anti-tumor cytotoxic function is a new therapeutic opportunity for the treatment of solid tumors." (PMID 36672396, 2023). "The genes PVR and NECTIN2, which encode for TIGIT ligands, were expressed by tumor epithelial, endothelial, fibroblasts, macrophages, and DCs in the TME." (PMID 38008725, 2023). "Multicolor IHC staining confirmed the interaction of NECTIN2-TIGIT on tumor sections from GC patients." (PMID 35999201, 2022). "NECTIN1 and NECTIN4 are most strongly expressed in tumor cells, but NECTIN2 and NECTIN3 are also expressed in some lymphocyte cell types, while TIGIT is largely expressed in Tregs and exhausted CD4+ T cells." (PMID 35995947, 2022). "TASCs, DC_LAMP3, and tumor cells, all highly expressed NECTIN2 and PVR (CD155), whose interaction with TIGIT blocks T-cell activation and proliferation." (PMID 35999201, 2022). "Upon the inhibition of the ubiquitin pathway, increased Nectin2 surface expression renders tumor cells more efficiently recognized and lysed by NK cells by mediating the CD226-dependent co-stimulation of both NK and CD8+ T cells." (PMID 36553083, 2022). "It has been shown that Nectin-2 expression is significantly correlated with clinical progression, as indicated by large tumor size and lymph node metastasis." (PMID 36553083, 2022). "The expression of mRNA and protein of nectin-2 is up-regulated in various cancer tissues, including breast, ovarian, and prostate cancer, compared to their adjacent non-tumor tissues." (PMID 36293219, 2022). "Although nectin-2 is highly overexpressed in the OV-90 cell line, the c12G1 antibody cannot be used as an anti-tumor agent in the form of an antibody itself." (PMID 36293219, 2022). "TIGIT binds to two ligands, CD155 (PVR) and CD112 (PVRL2, nectin-2), which are expressed by tumour cells and antigen-presenting cells in the tumour microenvironment." (PMID 35057760, 2022). "Binding to its ligands CD155 and CD112 (or nectin-2) expressed by tumor cells and antigen-presenting cells in the TME, TIGIT induces anergy of T cells and NKs, immune suppression, and tumor escape." (PMID 35712510, 2022). "Known ligands are PVR (CD155) and Nectin-2 (CD112), which are expressed by a variety of different tumor types." (PMID 34572949, 2021).
tumor (continued). "DNAM-1 recognizes the poliovirus receptor or CD155 and CD112 (nectin-2) on tumor cells which induce NK cell-mediated lysis." (PMID 34440725, 2021). "Both PVR and nectin-2 expressions are upregulated on tumor cells, which contributes to tumor recognition and killing." (PMID 33670993, 2021). "TIGIT and TACTILE/CD96 are inhibitory co-receptors expressed by both T and NK cells, and are linked to the CD112 (Nectin-2) and CD155 (PVR) expressed by APCs, infected cells and tumor cells." (PMID 34359767, 2021). "Studies have shown that NECTIN2 is an adhesion molecule that participates in tumor growth, metastasis, and tumor angiogenesis." (PMID 34610581, 2021). "Two major ligands for TIGIT are poliovirus receptor (PVR, CD155) and poliovirus receptor-related 2 (PVRL2, CD112, nectin-2), which are expressed by tumor cells as well as myeloid cells." (PMID 33581644, 2021). "MPDZ modulates DLL4-induced Notch signaling in the vasculature through physical interaction with DLL1 and DLL4, assisting their interaction with the adherents junction protein Nectin-2 and improving Notch signaling activity with tumor angiogenesis drop off." (PMID 34440260, 2021). "TIGIT expression impairs T/NK cells via binding to CD155 (PVR) and CD112 (Nectin2) expressed in myeloid cells and tumor cells." (PMID 33535613, 2021). "PVR (also known as CD155 or Necl-5) and Nectin-2 (also known as Pvrl2 or CD112) are two major ligands that are expressed on epithelial and myeloid cells of the tumor (Human Cell Atlas,2,3)." (PMID 32489646, 2020). "The known ligands for TIGIT are CD155 [also known as poliovirus receptor (PVR)] and CD112 (also known as nectin-2) that are expressed on myeloid, endothelial or tumor cells." (PMID 33117369, 2020). "TIGIT is expressed on both activated T and NK cells and interacts with two specific DNAM-1 (CD226) ligands, CD155 (PVR) and CD112 (nectin-2), which are expressed on both immune and tumor cells." (PMID 32610578, 2020). "PVR and Nectin-2 are expressed by tumor cells as well as myeloid cells, while TIGIT, CD96, and DNAM-1 are expressed on effector lymphoid cells." (PMID 32489646, 2020). "Two TIGIT ligands, CD155 (PVR) and CD112 (PVRL2, nectin-2), have been identified; they are primarily expressed on APCs (such as dendritic cells and macrophages) and tumor cells." (PMID 30863404, 2019). "The fact that FusOn-H2 can spread in these tumor cells indicates that HSV-2 gD can use nectin-2 for both entry and cell to cell transmission." (PMID 29765544, 2018). "We have shown that ADCC was the main mechanism of tumor regression of anti-Nectin-2 mAb, Y-443, for which binding of the Fc to FcγRIIIa is essential to maintain ADCC." (PMID 29723247, 2018). "To test if nectin-2 alone allows the entry of both Baco-1 and FusOn-H2 into tumor cells and it additionally allows cell-cell spreading of FusOn-H2, we infected CHO-N2 cells with both viruses." (PMID 29765544, 2018). "We subsequently developed an anti-Nectin-2 fully human mAb, Y-443, which has an in vivo anti-tumor effect on OV-90 and MDA-MB-231 xenograft models through an ADCC mechanism." (PMID 29723247, 2018). "We have previously reported that Y-443, one of the anti-Nectin-2 fully human mAbs, significantly inhibited tumor growth in a MDA-MB-231 mouse subcutaneous xenograft model with ADCC as the central mechanism of action." (PMID 29723247, 2018). "DNAM-1 recognizes CD155 (also known as Poliovirus receptor or PVR) and CD112 (Nectin-2) on tumor cells and induces NK cell-mediated lysis." (PMID 28955340, 2017). "This study first demonstrated that positive Nectin-2 expression significantly correlated with clinical progression, as indicated by large tumor size, lymph node metastasis, and tumor cell invasion." (PMID 26294807, 2015). "Nectin-2 is expressed on the surface of tumor cells, and its recognition by NK cells plays a role in antitumor immunity." (PMID 26294807, 2015).
tumor (continued). "DNAM-1 is a co-receptor expressed by virtually all NK cells and its stimulation by interaction with the members of the nectin family, PVR (CD155) and Nectin-2 (CD112), on tumor cells leads to NK cell activation and target cell lysis." (PMID 25889680, 2015). "To see if the anti-Nectin-2 mAbs exerted in vivo anti-tumor effects, we selected 2 representative mAbs, Y-187 from epitope bin VI and Y-443 from epitope bin VII, which showed different biological activities." (PMID 23758976, 2013). "This suggests a selective interaction pattern of NECTIN2-TIGIT in the tumor setting." (PMID 41394809, 2025). "Elevated TIGIT expression may contribute to an immunosuppressive tumor microenvironment by interacting with its ligands (e.g., PVR, NECTIN-2) expressed by stromal and malignant cells, thereby promoting T cell exhaustion and enabling tumor immune evasion." (PMID 40799645, 2025). "Additionally, St6galnac-I–deficient mouse LUAD tumors exhibited reduced association of Nectin2 with Tigit, indicating that St6galnac-I contributes to tumor immunosuppressive environment through T cell dysfunction mediated by Nectin2." (PMID 40371640, 2025). "Both Nectin-2 and Nectin-4 expressions were more pronounced at the invasive tumor margins." (PMID 40699695, 2025). "Additionally, γδT cells express DNAM-1 (CD226), which binds to CD155 (PVR) and CD112 (Nectin-2), further strengthening tumor recognition and immune activation." (PMID 40226616, 2025). "Consistently, administration of PTSO-pretreated hPBMCs resulted in reduced NECTIN2 gene expression in tumors, which may have facilitated the increased infiltration of anti-tumor T cells observed in treated mice relative to controls." (PMID 41010517, 2025). "Finally, we analysed the expression of those genes in our GeoMx data, which revealed decreased levels of almost all genes, bar PVR, VSIR and NECTIN2, in the primary tumour, compared to healthy tissues." (PMID 41168392, 2025). "We speculated that the communicative signal between TIGIT and NECTIN2 represented a crucial mechanism for LUAD tumor cells to establish the immunosuppressive microenvironment." (PMID 39474422, 2024). "To further confirm whether this tumor alleviation effect upon Nectin2 knockdown was brought about by neutrophils, we administrated A6K-siNectin2 in the neutrophil-depleted mice." (PMID 39261943, 2024). "Administration of A6K-siNectin2 in vivo tumors may have suppressed the tumor growth by acting on not only Nectin2 + TANs but also cancer cells that express Nectin2." (PMID 39261943, 2024). "We also found that an upregulation of the NK-cell cytotoxicity trigger molecule DNAM-1 on γδ T-cells expanded after exercise and β2-AR agonist infusion, and its ability to ligate with the PVR and Nectin-2 expressed by leukemic targets, were directly involved in the anti-tumor response." (PMID 38592213, 2024). "Interestingly, we observed marked upregulation of a series of immune checkpoints (e.g., CD86, CD80, HAVCR2 and LGALS9) in most tumor infiltrating myeloid cells, and a unique pattern in TAMs (e.g., NECTIN2, TNFRSF14, CD276 and TNFRSF9)." (PMID 38414027, 2024). "These immunosuppressive cells express high levels of TIGIT, an immune checkpoint molecule, establishing cellular communication with various tumor cells (such as DUSP1_fib, BASP1_fib, PDGFRA_fib, and IDO1_fib) expressing NECTIN2, thereby facilitating immune evasion of the tumor cells." (PMID 38443340, 2024). "The next question is whether the engagement of complement proteins influences PD-L1 and NECTIN2 expression on ascitic tumor cells." (PMID 38460015, 2024). "Moreover, we observed that the tumor cell marker gene EPCAM exhibited more similar spatial localization with the NECTIN2 than PVR gene in lepidic pattern, which is consistent with the results of scRNA-seq data." (PMID 39474422, 2024). "Nectin2 expression is thus upregulated in NB patients and correlates with advanced tumor staging." (PMID 36916296, 2023).
tumor (continued). "In these tumors, precluding the PVRIG/NECTIN-2 interaction might unleash a cytotoxic anti-tumor immune response and improve the clinical outcome." (PMID 36672396, 2023). "A surprising result was the correlation between nectin-2 expression and tumor location." (PMID 37958883, 2023). "Does serum nectin-2 concentration correlate with its tumor expression in CRC patients?" (PMID 37958883, 2023). "However, PVR and Nectin2 are also recognized by inhibitory receptors that are upregulated in tumor microenvironment and can counteract DNAM-1 activation, leading to NK cells hypo-functionality." (PMID 37760586, 2023). "TIGIT could be engaged with the two ligands, CD155 (PVR) and CD112 (PVRL2, Nectin-2), expressed by tumor cells and antigen-presenting cells in the tumor microenvironment." (PMID 38203670, 2023). "Therefore, to connect these data on tumor cell death with NK cell activation, we used B16F10 cells deficient in expression of CD155/PVR/Necl5 and CD112/Nectin2 and (Necl5 and Nectin2, hereafter), the ligands for the activating receptor DNAM-1 on NK cells." (PMID 35113018, 2022). "Besides, cytokines such as PVR and NECTIN2 also participate in building the tumor immunosuppressive microenvironment." (PMID 36685571, 2022). "Nectin-2 is an adhesion molecule that has a role in tumor growth, metastasis, and angiogenesis." (PMID 35330327, 2022). "TIGIT competes with CD226 to bind to PVR (CD155) and Nectin-2 (CD112) two molecules often up-regulated on tumor cells thus playing an important role in the NK-cell activity inhibition in part counterbalanced by the co-stimulatory activity exert by DNAM-1(CD226) receptor." (PMID 36291830, 2022). "Based on the mechanism underlying TIGIT-mediated regulation of anti-tumor immune responses, efforts have been made to enhance T or NK cell activity by blocking TIGIT binding to its ligands, PVR and nectin-2, with monoclonal antibodies (mAbs) for therapeutic interventions." (PMID 33670993, 2021). "We examined the expression of TIGIT and NECTIN2 in the lymphocytes and tumor cells, respectively." (PMID 34140495, 2021). "Similarly, NK-mediated lysis of tumor cells is enhanced after DNAM-1 (in NK cells) interacts with PVR or Nectin-2 (in target cells), whereas this effect is inhibited by treatment with a mAb targeting DNAM-1 or its receptor." (PMID 34433460, 2021). "Furthermore, we discovered multiple anti-Nectin-2 fully human monoclonal antibodies which inhibited tumor growth in in vivo subcutaneous xenograft models with antibody-dependent cellular cytotoxicity (ADCC) as the principal mechanism of action." (PMID 29723247, 2018). "The mechanism underlying the enhanced tumor cell killing may involve the increased expression of MICA, MICB, PVR, and Nectin-2 proteins on MM cells and the ligands of the activating receptors, NKG2D and DNAM-1." (PMID 27992381, 2017). "These functions of Nectin-2 implicate its possible roles in tumor cell survival and proliferation." (PMID 26294807, 2015). "The nectin-2 expression correlated with the tumor grade (p = 0.04)." (PMID 25690753, 2015). "In addition, we tested anti-Nectin-2 mAbs in several in vivo tumor growth inhibition models to investigate the primary mechanisms of action of the mAbs." (PMID 23758976, 2013). "JK and YI tested the in vivo anti-tumor effects of the anti-Nectin-2 mAbs." (PMID 23758976, 2013). "In addition to the observed cytoplasmic staining of cancer tissue predominantly with the adhesion molecule Nectin-4, in our further research, we determined stronger expression of both Nectins at the invasive edges of the tumor, although it was much weaker with Nectin-2." (PMID 40699695, 2025). "CD4_Exh and CD8_Exh cells, which often suffer functional impairments due to chronic antigen stimulation, may engage in specific communication with EC4 cells via the NECTIN2-TIGIT axis, potentially affecting the tumor-associated immunosuppressive microenvironment." (PMID 41394809, 2025).
tumor (continued). "It is worth noting that PVR, NECTIN2 have a low correlation with immune checkpoint receptors in tumors, which may be due to the almost non-existent expression of PVR and NECTIN2 on immune cells and explain the beneficial role of low expression of PVR, NECTIN2 in tumor survival assays." (PMID 39120585, 2024). "Notably, single-cell sequencing results demonstrated that tumor-associated macrophages (TAM) significantly inhibited tumor T-cell infiltration, and T cell immunoreceptor with Ig and ITIM domains–nectin cell adhesion molecule 2 (TIGIT–NECTIN2) interaction regulated the immunosuppressive environment." (PMID 36936956, 2023). "One hypothesis might be that the PVRIG/NECTIN-2 axis is a new negative feedback loop, either proper to the tumor liver microenvironment or associated with a specific context of immune response." (PMID 36672396, 2023). "DNAM-1 binds two main ligands also expressed on the surface of tumor cells or virus-infected cells, CD155 (poliovirus receptor, PVR) and CD112 (nectin-2)." (PMID 40211394, 2025). "In this study, we studied the role of ST6GalNAc-I in the modulation of NECTIN2/MUC5AC/VCAN for immune evasion and tumor angiogenesis during LUAD development." (PMID 40371640, 2025). "The IHC staining results for Nectin-2 and Nectin-4 in LSCC confirmed the expression of both molecules in the tumor parenchyma and the surrounding stroma." (PMID 40699695, 2025). "In particular, two main ligands have been identified for TIGIT: CD112 (Nectin-2) and CD155 (poliovirus receptor, PVR), which are broadly expressed on antigen-presenting cells (APCs) and tumor cells." (PMID 40508202, 2025). "Overall, our studies demonstrated that ST6GalNAc-I–induced tumor cell sialylation through NECTIN2 and MUC5AC contributes to immune evasion and tumor angiogenesis." (PMID 40371640, 2025). "The growth inhibitory effect was correlated to the expression of NECTIN1, NECTIN2, and ITGB6 by the tumor cell lines." (PMID 40955425, 2025). "TIGIT ligands (PVR, NECTIN2, NECTIN3) were predominantly expressed on tumor cells, while LAG3 ligands (H2-AB1, H2-AA, H2-EB1) were mainly expressed on macrophages and DCs." (PMID 40027748, 2025). "DNAM-1 (CD226) is a critical activating receptor on the surface of NK cells that mediates their activation by recognizing ligands such as Nectin-2 (CD112) and PVR (CD155), which are expressed on the surface of tumor cells." (PMID 40463500, 2025). "As an IC receptor within the IgSF, TIGIT interacts with ligands such as CD155 (PVR or Nectin-5), CD113 (PVRL3 or Nectin-3), CD112 (PVRL2 or Nectin-2) and PVRL4 (Nectin-4) to suppress T cell activity, facilitating tumour evasion of immune surveillance." (PMID 40994140, 2025). "DNAM1/CD226 is a potent activating receptor that has been shown to recognize two ligands overexpressed by tumor cells, namely PVR/CD155 which is considered as the main ligand and Nectin2/CD112." (PMID 39179536, 2024). "Another activating receptor involved in NK cell-mediated tumor cell killing is DNAM-1, which recognizes Nectin-2 (Nec-2, CD112) and the poliovirus receptor (PVR, CD155) ligands." (PMID 38731936, 2024). "In PM1, CD226 was expressed in CD27+ CD4+ and CD4+ Memory subpopulations, and corresponding ligands in tumor cells were TIGB2, NECTIN2 and PVR." (PMID 38528036, 2024). "Blockade of the CCL5–CCR5 axis or Nectin2 improved CD8+ T-cell activity and suppressed tumor growth in vivo." (PMID 39261943, 2024). "Nectin cell adhesion molecule 2 (NECTIN2), an upstream target of cytoskeletal regulation via SRC signaling, is an adhesion molecule that has been reported to play a role in tumor growth, metastasis and angiogenesis." (PMID 39085398, 2024). "The results showed that CD200, CD80 and TNFRSF14 were the highest in tumor tissues, CD274 (PDL1), CD86, LGALS9, NECTIN2, PDL2, PVR were lower than those in adjacent tissues but higher than those in normal tissues, and FGL1 was the lowest in tumor tissues." (PMID 39120585, 2024).